TALAM1 (TALAM1 transcript, MALAT1 antisense RNA)
Gene: Long non-coding RNA gene on chromosome 11 (65,499,045 to 65,507,432, reverse strand). Ensembl gene ENSG00000289740.
Gene Ontology:
Biological process: positive regulation of cell motility
Diseases named in the same sentence as TALAM1 in open-access papers:
TALAM1 is named in the same sentence as 12 diseases in open-access papers, as found by Europe PMC text mining. Sharing a sentence is not in itself a finding about the gene and the disease. The quoted sentences say what the papers report.
breast carcinoma (4 papers, 2019 to 2025). "Specifically, TALAM1 has been shown to facilitate motility of breast cancer cells within in vitro as well as in vivo migration assays utilizing immunocompromised mice." (PMID 40352330, 2025). "Previous reports on breast cancer have demonstrated that TALAM1 contributes to the stability of MALAT1, promoting the 3′ cleavage and maturation of MALAT1 and decreasing the migration and invasion of cancer cells." (PMID 37754231, 2023). "Here, we demonstrate that TALAM1 synergizes with MALAT1 during tumorigenesis in aggressive breast cancer." (PMID 31382922, 2019). "Here using a collection of breast cancer cells and in vitro and in vivo migration assays we characterized the dynamics of expression and demonstrated that TALAM1 regulates and synergizes with MALAT1 during tumorigenesis." (PMID 31382922, 2019). "Here we show that TALAM1 synergizes with MALAT1 on the regulation of the migratory capacity of human breast cancer cells." (PMID 31382922, 2019). "By regulating MALAT1, TALAM1 reveals the functional properties of natural antisense transcripts in gene regulation and cancer networks, raising new candidates for breast cancer targeting." (PMID 31382922, 2019). "Down-regulation of TALAM1 was shown to greatly impact on the capacity of breast cancer cells to migrate in vitro or to populate the lungs of immunocompromised mice." (PMID 31382922, 2019). "Overall, these results support a biological role for TALAM1 in breast cancer progression and discriminate a potential novel target stalling cancer invasiveness." (PMID 31382922, 2019). "By regulating the functional levels of MALAT1, down-regulation of TALAM1 leads to a synergistic biological effect characterized by a stronger decrease of the migration, invasion and expression properties of human breast cancer cells." (PMID 31382922, 2019). "To further characterize the presence and biological function of TALAM1 we decided to use human representative breast cancer cell lines with different biological and aggressiveness properties, a model known to be regulated by MALAT1." (PMID 31382922, 2019). "In addition, synergism of TALAM1 with Metastasis Associated Lung Adenocarcinoma Transcript 1 (MALAT1) was evidenced in the tumor characteristics and acquisition of aggressiveness of breast cancer." (PMID 37754231, 2023). "Additionally, we demonstrated that TALAM1 cooperates with MALAT1 in the regulation of the properties guiding breast cancer aggressiveness and malignancy." (PMID 31382922, 2019). "The positive correlation detected between MALAT1 and TALAM1 suggests that TALAM1 could share a biological role in the progression of human breast cancer, as reported for MALAT1." (PMID 31382922, 2019). "The lncRNA TALAM1 is the natural antisense transcript (NAT) at the MALAT1 locus, and it is involved in the migration and invasion of breast cancer cells." (PMID 37754231, 2023). "Strand-specific detection of MALAT1 and TALAM1 shown that both lncRNAs are significantly upregulated in all breast cancer cell lines tested comparing to the non-tumorigenic cell line." (PMID 31382922, 2019).
adenoma (1 paper, 2022). A neoplasm arising from the epithelium. "Therefore, we concluded that amplification of the region encoding MALAT1 and TALAM1 in 5 out of the 16 adenoma samples revealed cancer potential in these samples." (PMID 35887000, 2022). "Briefly, a general feature of the first group was the gain in adenoma tissue of chromosome 11, 11q13.1, encoding long non-coding RNA (lncRNA) MALAT1 and its antisense transcript TALAM1, in patients P1, P2, P3, P5, and P16." (PMID 35887000, 2022). "The second group consisted of patients with numerous chromosomal microdeletions in adenoma tissues compared to the adjacent tissue with no aberrations in the region encoding for MALAT1 or TALAM1 (P6, P7, and P10)." (PMID 35887000, 2022). "In the adenoma genome of patient P5, trisomy of three chromosomes (chr: 7 (α^ = 23%), 13 (α^ = 22%) and X (α^ = 11%)) was found, and at the same time gain of the region encoding for MALAT1 and TALAM1 (α^ = 100%)." (PMID 35887000, 2022). "Common features of patients P6, P7 and P10 in this second group were many microdeletions at 7q, 9p, 16p, 17q, and 20q in the genome of adenoma tissue compared to that of adjacent tissue, and likewise without the presence of MALAT1 or TALAM1 gain on chromosome 11 or any other gain." (PMID 35887000, 2022).
colorectal cancer (1 paper, 2022). A primary or metastatic malignant neoplasm that affects the colon or rectum. "The aberrations found in this study (losses of TSC2, COL1A1, NOTCH1, MIR4673 and GNAS, and gains of MALAT1 and TALAM1) may serve as candidate biomarkers for early detection of colorectal cancer onset." (PMID 35887000, 2022).
COVID-19 (1 paper, 2021). A disease caused by infection with severe acute respiratory syndrome coronavirus 2. "Interestingly we found six lncRNAs (TALAM1, DLEU2, and UICLM CASC18, SNHG20, and GNAS) involved in the protein-coding DEG-lncRNA network; which might be served as potential biomarkers for COVID-19 patients." (PMID 34975833, 2021).
HIV-1 infection (1 paper, 2026). The type species of lentivirus and the etiologic agent of acquired immunodeficiency syndrome (AIDS). "Together, these findings provide an initial characterization of lncRNA responses to HIV-1 infection in a human microglial cell line and identify TALAM1 and LINC00702 as candidates for future functional studies in the context of viral infection and neuroinflammation." (PMID 41977450, 2026). "TALAM1 was predominantly cytoplasmic under basal conditions but shifted toward nuclear enrichment upon HIV-1 infection, whereas LINC00702 remained primarily nuclear regardless of infection status." (PMID 41977450, 2026).
lung adenocarcinoma (1 paper, 2023). A carcinoma that arises from the lung and is characterized by the presence of malignant glandular epithelial cells. "The results showed that the expression of TALAM1 increased in the lung adenocarcinoma cell lines PC9 and A549, with a statistically significant increase in A549 cells." (PMID 37754231, 2023). "We found a critical contribution of the RUNX2 TF in transcriptional repression of TALAM1 in lung adenocarcinoma." (PMID 37754231, 2023). "Additionally, we performed shRNA-mediated knockdown of RUNX2 in a lung adenocarcinoma cell line to confirm its regulatory role in the expression of TALAM1, a long noncoding RNA (lncRNA) identified as a target of RUNX2 TF in this work." (PMID 37754231, 2023). "Together, these results indicated that the RUNX2 TF might participate in the transcriptional control of TALAM1 in lung adenocarcinoma." (PMID 37754231, 2023). "In addition, we performed shRNA-mediated knockdown of RUNX2 in this lung adenocarcinoma cell line to confirm the regulatory role of RUNX2 in TALAM1 expression." (PMID 37754231, 2023). "Thus, shRNA-mediated knockdown of this TF prevents silencing of the TALAM1 gene in the A549 lung adenocarcinoma cell line." (PMID 37754231, 2023). "RUNX2-depleted cells exhibited higher TALAM1 levels, suggesting that the RUNX2 TF promotes transcriptional repression of TALAM1 in lung adenocarcinoma." (PMID 37754231, 2023). "We performed ChIP-seq analysis in tumor samples of a patient diagnosed with lung adenocarcinoma, and we reported the enrichment of RUNX2 in the promoters of genes such as BZW1, CARMIL1, FLOT1, and TALAM1." (PMID 37754231, 2023). "We next investigated whether TALAM1 transcription in A549 lung adenocarcinoma cells is modulated by the transcription factor RUNX2, which was observed to bind to the TALAM1 promoter region." (PMID 37754231, 2023). "In addition, we evaluated TALAM1 expression in the PC9 and A549 lung adenocarcinoma cell lines." (PMID 37754231, 2023).
lung carcinoma (1 paper, 2023). "In this paper, we identified TALAM1 (Metastasis Associated Lung Adenocarcinoma Transcript 1) as a genetic target of the RUNX2 TF in lung cancer and then performed functional validation of the main findings." (PMID 37754231, 2023). "This relationship provides an understanding of the role of the RUNX2 transcription factor in the lung tumor context and poses new questions about the functional role of the lncRNA TALAM1 in lung cancer that need to be answered." (PMID 37754231, 2023). "To evaluate the expression profile of the lncRNA TALAM1 in human lung cancer, we performed qPCR analysis on five primary lung cancer samples and six samples of metastatic origin." (PMID 37754231, 2023). "In this work, we found overexpression of TALAM1 in lung cancer (cell lines and primary cultured cells), and its expression was significantly higher in primary lung cancer samples." (PMID 37754231, 2023). "Specifically, we found that RUNX2 contributes to controlling the expression of lncRNA TALAM1 in lung cancer." (PMID 37754231, 2023). "In this work, we demonstrated for the first time that the RUNX2 TF in lung cancer cells functions as a repressor of the expression of the lncRNA TALAM1." (PMID 37754231, 2023). "Although there are numerous studies on the role of MALAT1 in lung cancer, there are still no reports on TALAM1 expression profile and the probable mechanisms associated with its transcriptional regulation." (PMID 37754231, 2023). "Since TALAM1 is a transcriptional target of the RUNX2 TF, its function in lung cancer is likely related to the transcriptional regulation of these genes through their interaction with Polycomb group proteins; however, further studies are required to verify this hypothesis." (PMID 37754231, 2023).
cancer (3 papers, 2019 to 2023). A tumor composed of atypical neoplastic, often pleomorphic cells that invade other tissues. "Having the knowledge that MALAT1 was upregulated in cancer tissues, we asked whether non-cancerous tissues would increase MALAT1 / TALAM1 expression after a signal driving migration." (PMID 31382922, 2019).
tumor (2 papers, 2022 to 2023). "Reports in the literature describing the regulatory mechanisms of TALAM1 and its function in the tumor context are scarce." (PMID 37754231, 2023).
infection (1 paper, 2026). The state of being infected such as from the introduction of a foreign agent such as serum, vaccine, antigenic substance or organism. "Validation by RT-qPCR confirmed the upregulation of TALAM1 and LINC00702 at 24 h post-infection." (PMID 41977450, 2026).
TALAM1 also shares sentences with these, for which no sentence is quoted: triple-negative breast carcinoma (1 paper); viral infection (1).